WNT1 (Wnt family member 1)
Diseases named in the same sentence as WNT1 in open-access papers (continued):
Sharing a sentence is not in itself a finding about the gene and the disease.
osteoporosis (continued). "Homozygous mutations in WNT1, causing recessive OI, are characterized with fractures, short stature, osteoporosis, vertebral compression, and variable neurological problems, while heterozygous mutations in WNT1, causing dominant OI, present with early-onset osteoporosis." (PMID 39127989, 2024). "In addition, rarer cases of monogenic osteoporosis are associated with mutations in genes involved in WNT1 signaling." (PMID 37958752, 2023). "Thus, biallelic nonsense or frameshift mutations of WNT1 can also lead to osteogenesis imperfecta, earlier onset of fragility fractures, and the development of early-onset osteoporosis." (PMID 37958752, 2023). "Since LRP5, PLS3, and WNT1 pathogenic variants cause osteoporosis, this was expected." (PMID 37277619, 2023). "Heterozygous WNT1 mutations result in a mild reduction in Wnt/β-Catenin signaling, leading to mild bone disease, such as early-onset osteoporosis with multiple fractures, mainly affecting the spine; however, growth is not affected and extra-skeletal features are not common in these cases." (PMID 36004351, 2022). "We confirm that the heterozygous WNT1 mutation could cause a variable bone fragility and low turnover osteoporosis." (PMID 36004351, 2022). "The question of whether anti-sclerostin antibodies might be effective in the treatment of OI or early-onset osteoporosis caused by heterozygous WNT1 mutations remains to be elucidated." (PMID 36004351, 2022). "Quite recently, heterozygous Wnt family member 1 (WNT1) mutations have been found in adults with autosomal dominant early-onset osteoporosis, overlapping in some aspects with the same mutation (in this case involving both alleles), and causing severe osteogenesis imperfecta." (PMID 34948434, 2021). "We present the case of two brothers with early osteoporosis who were found to have a heterozygous variant of unknown significance in the WNT1 gene, c.1060_1061delCAinsG (p.H354Afs*39)." (PMID 34458510, 2021). "Some of this early-onset forms of osteoporosis are caused by heterozygous WNT1 mutations." (PMID 32328030, 2020). "Loss-of-function variants in LRP5 and WNT1 may lead to early-onset osteoporosis." (PMID 34236445, 2022). "Moreover, heterozygous WNT1 mutations have been found in adults with early-onset osteoporosis." (PMID 36004351, 2022). "Given its central role in bone metabolism by activating osteoblasts and promoting osteoclastogenesis, the canonical WNT1 pathway has become a key target for novel osteoporosis therapeutics." (PMID 41128774, 2025). "As the proband’s skeletal phenotype was more severe than those reported earlier for WNT1-related osteoporosis, bone biopsy was obtained to further evaluate bone quality." (PMID 41128774, 2025). "In contrast, our 27-yr-old proband and his 59-yr-old mother had severe osteoporosis with multiple fragility fractures and very low BMD despite harboring the same WNT1 variant in a heterozygous state." (PMID 41128774, 2025). "A nivel paracrino, también parecen existir conexiones entre el FGF23 y algunas alteraciones del remodelado óseo, como las mutaciones del Wnt1 que ocasionan osteoporosis precoz y fractura prevalente." (PMID 38634083, 2024). "Given that the role of LRP5, PLS3, and WNT1 in the development of osteoporosis was only discovered 10–15 years ago, and the rarity of these pathogenic variants, their associated morbidity and prognosis are still largely undetermined." (PMID 37277619, 2023). "WNT1 and PLS3 pathogenic variants cause early-onset, severe osteoporosis with low BMD and frequent fractures." (PMID 36157448, 2022). "In a recent study, a comparison between Wnt1-cKO in osteoblasts and cKO in monocytes showed the development of general osteoporosis with high bone fragility only in the osteoblast cKO." (PMID 35052478, 2022). "WNT1 and PLS3 are two crucial factors regulating bone metabolism and abnormalities in their signaling have been linked to severe early-onset osteoporosis." (PMID 36157448, 2022).
osteoporosis (continued). "Diseases associated with WNT1 include osteogenesis imperfecta type Xv and BMD quantitative trait locus 16 (osteoporosis)." (PMID 35401685, 2022). "Quantitative real-time PCR shown that Wnt1, Wnt5a, Wnt7a, and Wnt9a mRNAs were lower expressed in osteoporosis derived EVs." (PMID 34375951, 2021). "WNT1, encoding the Wnt family member 1, is another important player in the WNT-β-catenin signalling pathway underlying osteoporosis." (PMID 33945105, 2021). "Biomarker analysis performed in serum of patients with WNT1 osteoporosis revealed increased levels of fibroblast growth factor 23 —a bone-derived hormone—, and a disease-specific miRNA signature." (PMID 33945105, 2021). "Missense mutation c.652T>G (p.C218G) in WNT1, and an X-linked form resulting from a splice mutation c.73-24T>A in PLS3 are associated with osteoporosis in children." (PMID 32733380, 2020). "In contrast, cartilaginous tissue deterioration does not seem to be a typical characteristic of PLS3 osteoporosis and the difference to WNT1 osteoporosis is evident when comparing the spinal structures and stature in PLS3 and WNT1 mutation-positive subjects." (PMID 32655496, 2020). "We have reported altered miRNA pattern in patients with WNT1 osteoporosis, with two upregulated and six downregulated miRNAs, as compared with age and sex-matched mutation-negative controls from the same family." (PMID 30858824, 2019). "Despite great research efforts, the management of WNT1-related osteoporosis remains challenging." (PMID 41128774, 2025). "Despite proven benefits of denosumab in postmenopausal osteoporosis, its impact in WNT1 osteoporosis remains unclear." (PMID 41128774, 2025). "Research on romosozumab in WNT1 osteoporosis; however, remains scarce." (PMID 41128774, 2025). "In previous cases of WNT1 osteoporosis, the first fractures have been lactation-induced." (PMID 41128774, 2025). "We aimed to investigate if plasma lipocalin-2 could be utilized as a biomarker for WNT1 and PLS3 osteoporosis and to evaluate the association between lipocalin-2 and other parameters of bone metabolism." (PMID 36157448, 2022). "Moreover, it is evident that the identification of a specific receptor mediating the influence of WNT1 on bone formation and matrix integrity might pave the way to develop additional osteoanabolic treatment options for various bone loss disorders, including osteoporosis." (PMID 34759273, 2021). "A spontaneous mutation in WNT1 (one of the major WNT ligands regulating bone homeostasis) is present in the swaying (Wnt1sw/sw) mouse, wherein a recessive mutation causes osteogenesis imperfecta and heterozygous mutation causes the early onset of osteoporosis." (PMID 33923673, 2021). "From those results, we deduced that spinal cartilaginous deterioration is a distinct feature of WNT1 osteoporosis and SNs, since prevalent also in children, could possibly predict future VCFs." (PMID 32655496, 2020). "WNT1 mutation affects WNT/β-catenin signaling that might affect osteocyte function, and causes an imbalance in bone homeostasis resulting in osteoporosis." (PMID 32733380, 2020). "Homozygous WNT1 pathogenic variants are a cause of OI type XV, whereas heterozygous pathogenic variants and variants in the LRP5 gene, associated with the Wnt pathway, cause osteoporosis." (PMID 33228694, 2020). "WNT1 encodes a key protein in bone development and bone mass; therefore, we speculate that the involvement of FGFR2 in WNT signaling in bone tissue could lead to an osteoporosis phenotype." (PMID 40362441, 2025). "The integration of multi-omics data from human skeleton delineates how WNT1 regulates the differentiation and maturation of skeletal progenitors, which will provide a new direction for the treatment strategy of type XV OI and relative low bone mass diseases such as early onset osteoporosis." (PMID 39126373, 2024).
osteoporosis (continued). "Given the young age of our proband and the absence of secondary causes of osteoporosis, we hypothesized a genetic origin for the bone disease which was indeed confirmed by the finding of a heterozygous missense variant of the WNT1 gene." (PMID 36004351, 2022). "Overall, the treatment results with conventional osteoporosis medications have not been optimal as several of the WNT1 mutation-positive adults have developed significant skeletal pathology with extensive spinal compression fractures despite several years of treatment." (PMID 34236445, 2022). "No renal abnormality has previously been linked to WNT1 or PLS3 osteoporosis." (PMID 36157448, 2022). "In contrast, we have previously reported increased prevalence of SNs, enlarged intervertebral discs and endplate deterioration in WNT1 osteoporosis, which we hypothesized to arise from aberrant WNT pathway activation and its consequent impact on the coupled osteogenesis and chondrogenesis." (PMID 32655496, 2020). "Identifiable risk factors include a low body mass index (BMI), reduced physical activity during adolescence, a strong family history of osteoporosis, and genetic variations in the LRP5 and WNT1 genes." (PMID 39703866, 2024). "The current study investigated whether lipocalin-2 could be a novel biomarker for WNT1 and PLS3 osteoporosis and explored its relationship to other parameters of bone and mineral metabolism." (PMID 36157448, 2022). "Given the reported link to DKK1 and its significance in bone metabolism, we sought to evaluate the significance and utility of lipocalin-2 as a novel biomarker in WNT1 and PLS3 osteoporosis and its correlations with other parameters of bone turnover as well as with parameters of iron metabolism." (PMID 36157448, 2022). "FOXO1, BMP4, WNT1, and EGFR in Cluster 2 are related to osteoporosis." (PMID 34777562, 2021). "This suggests that WNT1 and PLS3-mediated osteoporosis might have a similar mechanism of disease progression." (PMID 32733380, 2020). "However, the role of lipocalin-2 in WNT1 and PLS3 osteoporosis is unknown." (PMID 36157448, 2022). "In addition, the results of our study demonstrated that the mRNA levels of Wnt1, Wnt5a, Wnt7a, and Wnt9a were lower in osteoporosis-derived EVs than in non-osteoporosis-derived EVs, while DKK mRNA was up-regulated in osteoporotic individuals compared to non-osteoporotic individuals." (PMID 34375951, 2021). "Our results suggest that lipocalin-2 is not a specific biomarker for WNT1 and PLS3 osteoporosis, but the correlation between lipocalin-2 and FGF23 indicates an association between these markers in bone biology." (PMID 36157448, 2022). "In conclusion, our study demonstrates that the circulating levels of lipocalin-2 are not altered in WNT1 and PLS3 osteoporosis, and therefore cannot be used as a metabolic biomarker in the diagnosis or for monitoring these two monogenic conditions." (PMID 36157448, 2022). "Quantitative real-time PCR shown that Wnt1, Wnt5a, Wnt7a, and Wnt9a mRNAs were lower expressed in osteoporosis derived EVs, while DKK mRNA was up regulated in osteoporosis compared to non-osteoporotic individuals." (PMID 34375951, 2021).
colorectal cancer (36 papers, 2006 to 2025). A primary or metastatic malignant neoplasm that affects the colon or rectum. "Re-expression of sFRP1 in the colorectal cancer cell line HCT116 led to a reduction in nuclear β-catenin, while inhibition of WNT1 signalling by a function-blocking antibody caused apoptosis in primary colorectal cancer cells and cell lines." (PMID 16523202, 2006). "In terms of treatment, blocking Wnt1 has been observed to induce apoptosis of colorectal cancer cells." (PMID 39071493, 2024). "Overall, our findings shed light on the intricate interactions between TET1, Wnt1, and specific miRNAs in colorectal cancer (CRC) and their potential implications for diagnosis and treatment." (PMID 39495308, 2024). "Previously, miR-200b-3p was reported to restrain colorectal cancer cell growth and induce apoptosis by blocking the Wnt/β-catenin pathway through targeted inhibition of Wnt1 expression." (PMID 37165386, 2023). "PEG10 overexpression promoted HCT116 colorectal cancer cell proliferation and inhibited apoptosis via increasing Wnt1 and β-catenin expression." (PMID 33506057, 2021). "For example, the positive expression of WNT1 was correlated with a short overall survival time and involved in lung cancer and colorectal cancer metastasis." (PMID 34287269, 2021). "In colorectal carcinoma tissues, the results of RT-qPCR also showed that the expression of WNT1 mRNA was increased, compared with normal colon tissues." (PMID 34657551, 2021). "For example, colorectal-carcinoma-derived EVs contain Wnt1 and enhance colorectal carcinoma cell proliferation and migration through Wnt/β-catenin signaling, a pathway associated with EMT activation." (PMID 34769139, 2021). "Our model also predicted a high binding affinity between Wnt1 and CORIN‒Fz1, which have been indirectly linked through the negative regulation of Wnt1-induced β-catenin accumulation in colorectal cancer cells by CORIN’s major substrate, ANP." (PMID 31454915, 2019). "In a mouse model of Wnt1-driven colorectal cancer, tumour formation was reduced in Hmga2−/− mice, suggesting a role for Hmga2 in cancer development." (PMID 30228296, 2018). "To investigate the effect of hypoxia on Wnt/β-catenin signaling in colorectal-cancer cells, we thus examined the quantitative changes in the expression of positive (Wnt1, Lef1, cyclin D1) regulators of Wnt/β-catenin signaling with or without hypoxia." (PMID 26965643, 2016). "Specific Wnt ligands and receptors are found to be overexpressed in many tumors; monoclonal antibodies developed against Wnt-1 and Wnt-2 demonstrate Wnt inhibition leading to tumor suppression in melanoma, sarcoma, colorectal cancers, non-small cell lung carcinoma, and mesothelioma." (PMID 33607955, 2021). "Wnt1, one of the key ligands in β-catenin regulation, has been described for its prognostic role in several types of malignant tumors including non-small cell lung cancer, renal cell carcinoma, and colorectal cancer." (PMID 30814912, 2019). "Wnt1-LateEx tumor susceptibility is probably influenced by age-related changes that increase the risk of developing Hras1-activating mutations, as is the case for KRAS mutations in colorectal cancer." (PMID 31213486, 2019). "Blockade of Wnt-1 signalling induces apoptosis in human colorectal cancer cells." (PMID 24015932, 2013). "Therefore, inhibiting Wnt1 may potentially suppress the growth of colorectal cancer through epigenetic modifications." (PMID 39495308, 2024). "Klf3 is a transcription factor that plays a pivotal role in activating WNT1 and WNT/β-catenin signaling pathways, which are key drivers of colorectal cancer progression." (PMID 40427657, 2025). "Consistent with the microarray data, in both wnt1 transfected HEK293T cells and colorectal cancer cells, henryin inhibited Wnt-responsive reporter activity in a dose-dependent manner." (PMID 23844215, 2013).
colorectal cancer (continued). "Through non-canonical Wnt signaling, colorectal cancer cell-derived SEV Wnt1 can increase colorectal cancer cell proliferation and migration." (PMID 38243280, 2024). "Exosomal Wnt1 protein enhances the proliferation and migration of colorectal cancer by activating non-canonicial Wnt signaling." (PMID 31799196, 2019). "In the livers of colorectal cancer patients, used as negative control for β-catenin and wnt1, no cytoplasmic β-catenin or wnt1 expression was observed in the normal-appearing liver cells." (PMID 28218651, 2017). "Functions of miR-130a-3p in colorectal cancer (CRC) and contributions of Wnt1 pathway modulation, however, have not been examined, hence the exploration on these two aspects." (PMID 34657551, 2021). "According to literature data, high expression of WNT1 genes and low expression of noncanonical WNT5A correlating with cytoplasmic and nuclear β-catenin are observed in colorectal cancer; all these three characteristics are indicative of the shortened recurrence-free survival." (PMID 37345102, 2023).